ID2 (inhibitor of DNA binding 2)
Diseases named in the same sentence as ID2 in open-access papers (continued):
Sharing a sentence is not in itself a finding about the gene and the disease.
tumor (continued). "Accordingly, Bcl3 knockdown results in decreased Id1 and Id2 expression, with tumor cells becoming more sensitive to chemotherapeutic drug-induced apoptosis." (PMID 28122577, 2017). "Id2 is overexpressed in Hodgkin lymphoma tumor cells and suppresses the expression of B cell specific genes." (PMID 28122577, 2017). "In medulloblastoma the Id2 and Id3 proteins are overexpressed and promote tumor cell proliferation, whereas the Id1 protein has been found to be expressed in the tumor vessels, thus promoting tumor angiogenesis." (PMID 28122577, 2017). "ID2 suppressed ROS production, enhanced tumor cell survival, and protected mitochondria from damage, during glucose deprivation." (PMID 28206987, 2017). "Our data indicate that the expression level of ID2 in GBM cells can predict the sensitivity of GBM-derived tumor cells to decreased glucose levels." (PMID 28206987, 2017). "Id-1/Id-2 further binds to p62, and be transported to autolysosomes for degradation, thus regulating the differentiation of tumor cells and reducing the proportion of stem cell-like cancer cells." (PMID 29079782, 2017). "ID2 suppression of ROS production reduced mitochondrial damage and enhanced tumor cell survival during glucose deprivation." (PMID 28206987, 2017). "We further demonstrated, for the first time, that the hypoxia-induced CSC-sphere formation (by a CD44+ subpopulation) in vitro and tumor metastasis/dissemination in vivo were markedly suppressed by knocking down Id2 expression." (PMID 26965643, 2016). "We further demonstrated, for the first time, that the degree of hypoxia-induced CSC-sphere formation (CD44+ subpopulation) in vitro and of tumor metastasis/dissemination in vivo were markedly suppressed by knocking down Id2 expression." (PMID 26965643, 2016). "We further demonstrated, for the first time, that hypoxia-induced CSC sphere formation (CD44+ subpopulation), and the expression of stem-cell markers in vitro and tumor metastasis/dissemination in vivo were markedly suppressed by knocking down Id2 expression." (PMID 26965643, 2016). "After completing our in vitro experiments, we investigated the in vivo effect of Id2 knockdown on tumor metastasis/dissemination using a mouse model." (PMID 26965643, 2016). "The prior studies clearly describe indirect evidence for T-cell immunity as a mechanism of tumor rejection following Id2-kd/checkpoint blockade therapy." (PMID 26079374, 2015). "Taken together these results suggest that Id2-kd N2a cells provide a safe and effective source of tumor antigenicity and in combination with checkpoint blockade induce potent tumor immunity." (PMID 26079374, 2015). "Id2-kd N2a cells induced immunity in a syngeneic immune-competent mouse model, yet these tumor cells grew unabated in immune-compromised hosts." (PMID 26079374, 2015). "Our results suggest the possibility that the enhanced expression of Mxd1 suppresses ileal-tumor initiation in Apc Id2 mice." (PMID 26163528, 2015). "We have shown here direct genetic evidence that Id2 plays a crucial role in ileal tumor initiation in ApcΔ716 mice." (PMID 26163528, 2015). "Id2-kd N2a cells were vaccinated into the left leg of mice, three days following inoculation of wild type Neuro2a tumor cells in the right leg, and tumor growth was monitored." (PMID 26079374, 2015). "We subsequently tested irradiated (35 Gray) Id2-kd N2a cells as a whole tumor cell vaccine antigen source in combination with anti-CTLA-4 antibody against AgN2a and found that 60% of mice eradicated established tumors." (PMID 26079374, 2015). "We have demonstrated here that Id2 plays an essential role in ileal tumor initiation in ApcΔ716 mice." (PMID 26163528, 2015). "To investigate the potential role of Id2 in intestinal tumorigenesis, we first determined the mRNA levels of Id2 in the tumor epithelium of ApcΔ716 mice by qRT-PCR analysis." (PMID 26163528, 2015).
tumor (continued). "When Id2 is suppressed, the TGFβ pathway is activated inducing phenotypic transition to a less proliferative, anoikis resistant phenotype allowing the tumor cells to survive unfavorable or stressful conditions." (PMID 24376712, 2013). "The tumor-promoting properties of Id1, Id2, and Id3 are at least partially shared by Id4 also: Id4 has been shown to promote neoplastic transformation/growth." (PMID 23342267, 2012). "In a related study, low level of Sema3F expression was observed in highly metastatic human tumor cell lines due to Id2-mediated repression of gene transcription, which possibly accounts for the enhancement of tumor cell migration and invasion." (PMID 23050142, 2012). "Contrary to these observations, studies have also demonstrated pro-tumor function of Id4 that is consistent with its other family members Id1, Id2, and Id3." (PMID 23342267, 2012). "ID2 expression in tumor cells from the 62 NSCLC patients was highly diverse both in terms of intensity and localization." (PMID 19129913, 2009). "Overexpression of Id2 in ERα-positive epithelial tumor cells indeed increases the cells' invasive potential through a novel mechanism independent of dimerization to basic helix-loop-helix factors." (PMID 19257909, 2009). "Out of 62 NSCLC patients, a large proportion (98%, 61/62) expressed ID2 protein almost exclusively in tumor cells (median of global staining score = 3; range 0 to 18)." (PMID 19129913, 2009). "These controversial functional consequences of Id2 on tumor growth and invasion suggest the diverse nature of Id2 target signaling pathways in different cell contexts." (PMID 19257909, 2009). "Expression of progenitor cell markers in tumor foci of compound mice also differ in Id2 expression at late tumor stages when positive cells were very rare." (PMID 19551151, 2009). "Overexpression of Id2 is frequently observed in various human tumors, but its role for invasion potential in tumor cells is dispute." (PMID 19257909, 2009). "More recent studies have demonstrated that ID2 is involved in tumor progression in several cancer types such as prostate or breast." (PMID 19129913, 2009). "In this paradigm, the aberrant accumulation of Id2 and the subsequent E-cadherin down-regulation as we described should provide a selective growth advantage in the tumor microenvironment by increasing the probability of invasion and metastasis." (PMID 19257909, 2009). "Like FAS, ID over-expression correlates with tumor development in an array of cancers, and knockdown of ID2/ID3 induces growth arrest and apoptosis." (PMID 17565694, 2007). "While 30% of poorly differentiated ESCC expressed low-level cytoplasmic Id-2, the same was observed in only 7% of well or moderately differentiated tumours." (PMID 18000500, 2007). "Similarly, we observed a significant negative correlation between the number of deletions attributed to ID2 and tumor latency (R=−0.15; P=0.0042)." (PMID 40161734, 2025). "Directly regulates anti-tumor CD8+ T cell responses via ID2-dependent IL-12 signaling pathway." (PMID 41181090, 2025). "Additionally, the antioxidant properties of dietary fiber breakdown products can stimulate the proliferation and anti-tumor response of CD8+ T cells by upregulating the expression of ID2, thereby amplifying the anti-tumor effect." (PMID 40260237, 2025). "In GC, USP1 has been recently reported to promote tumor metastasis by stabilizing ID2 expression." (PMID 38366146, 2024). "Our study revealed significant overexpression of ID2 in various malignant tumor cells." (PMID 38195969, 2024). "In vivo experiments also showed that ID2 can promote tumor growth." (PMID 38254880, 2024). "Considering that Texprog cells but not terminally exhausted T cells can respond to anti-PD-1 therapy, we treated tumor-bearing mice with PD-1 blockade and found that Id2 deletion impaired the generation or maintenance of Slamf6+ Texprog cells that can respond to PD-1 blockade." (PMID 38287103, 2024).
tumor (continued). "The expression of ID2 was significantly higher in tumor compared to normal tissues." (PMID 38195969, 2024). "ID2 regulates tumor progression through distinct molecular signaling pathways." (PMID 38195969, 2024). "An LSD1 inhibitor GSK2879552 can rescue the Id2 knockout phenotype in tumor-bearing mice." (PMID 38287103, 2024). "Our current study validate TRIM69 as a mutually exclusive E3 ligase targeting EYA4 for polyubiquitylation and turnover, thereby perturbing its ability to deactivate β-catenin/ID2 pathway and suppress cell proliferation, self-renewal as well as tumor development of PDAC cells." (PMID 36741265, 2023). "This study revealed that the manipulation of ID2 via SMURF2 may control tumor progression and contribute to the development of novel targeted antitumor drugs." (PMID 37497010, 2023). "Only the nuclear expression of ID2 was negatively correlated with tumor grade 22." (PMID 37497010, 2023). "We found that ID2 is a tumor-promoting factor that promotes the progression of NSCLC." (PMID 37497010, 2023). "Relevant studies have indicated that Id2 might be dysregulated in tumor progression in several cancer types, such as prostate, breast, colon and rectal, head and neck, and central nervous system cancers." (PMID 35982951, 2022). "Furthermore, IPW-mediated miR-29c upregulation suppressed the ID2 expression and reduced the tumor initiating stem cell population." (PMID 35078502, 2022). "Together, these results suggest that ID2 may function as a tumor suppressor in hematopoietic malignancies." (PMID 35775482, 2022). "Downregulated genes include: 1) Immune system activators, such as CD86; 2) blood tumor suppressors ID2 and KLF4; 3) CEBPB, CEBPB is a BCR/ABL negative regulator gene, which can inhibit the proliferation of BCR/ABL-positive cells, and promote cell differentiation." (PMID 36699453, 2022). "The different roles of ID2 in different tumor types could be attributed to heterogeneity in the presence and expression levels of its interacting partners, the subcellular localization of ID2, and the expression signature of ID2 transcriptional target genes." (PMID 35729325, 2022). "In addition, IHC results also showed that ID2 expression was significantly down-regulated in tumor tissues." (PMID 34746132, 2021). "In addition to MYC, many tumor-associated genes such as RUNX1, FOSL2, BCL3 and ID2 are driven by SEs in diverse tumor types." (PMID 33628735, 2020). "Future studies will be required to assess whether monitoring ID2 mRNA or protein levels in primary tumours or in plasma samples could provide a prognostic biomarker for patients at higher risk of relapse in the brain." (PMID 30642388, 2019). "Finally, to confirm that the expression of Id2 and Aldh3a1 is upregulated in tumour cells colonising the brain in-vivo, 4T1 tumour cells were freshly isolated from the brains, lungs, and primary tumours and immediately analysed by RT-qPCR." (PMID 30642388, 2019). "Finally, we demonstrate that either ectopic expression of ID2 or BMP7-induced ID2 expression protects tumour cells from anoikis." (PMID 30642388, 2019). "Consistent with our previous findings, both Id2 and Aldh3a1 were significantly upregulated in tumour cells isolated from the brain compared with the primary tumour, with a higher expression of these genes in the brain-derived cells compared with those isolated from the lungs." (PMID 30642388, 2019). "Since we observed increased inflammation and age dependent plasticity of Treg cell populations in peripheral compartment of Id2EmGFPFoxp3YFP−Cre mice, we tested whether Treg cell-specific ectopic expression of Id2 can alter anti-tumor immunity." (PMID 30413714, 2018). "We recently reported that Id2 is involved in the tumor initiation process, and Id2 deficiency does not promote carcinogenesis of intestinal adenoma induced by Apc gene mutation." (PMID 29463648, 2018).
tumor (continued). "It has been proposed that in androgen-dependent prostate cancers androgen might regulate proliferation, apoptosis and tumor suppression via Id1/Id3, Id2 and Id4 regulation, respectively." (PMID 28122577, 2017). "In contrast, lack of this regulation in androgen-independent cancers might lead to cell proliferation (Id1 and Id3 up-regulation), cell survival (Id2 down-regulation) and decreased tumor suppression (Id4 down-regulation)." (PMID 28122577, 2017). "However, the specific role of Id2 in the self-renewal and tumor initiation of colorectal CSCs is largely unexplored." (PMID 26965643, 2016). "Earlier studies have shown that Id2 contributes to tumor proliferation." (PMID 26163528, 2015). "Changes induced by targeting Id2 in the tumor cell could vary from increased antigenicity, enhanced antigen presenting cell uptake or loss of immune-suppressive or immune-evasive mechanisms." (PMID 26079374, 2015). "In such a case the presence of Id2 protein even in the single neoplastic cell could confirm its crucial role in tumor development." (PMID 25771836, 2015). "On the other hand, we have demonstrated here that loss of Id2 inhibits tumor initiation rather than tumor expansion in ApcΔ716 mice." (PMID 26163528, 2015). "There is also a hypothesis concerning the influence of Id2 proteins on primary neoplastic cells (tumor stem cells)." (PMID 25771836, 2015). "This raises the possibility that Id1 and Id3 compensate for the function of Id2 in the duodenal- and jejunal-tumor initiation that is not affected by the loss of Id2." (PMID 26163528, 2015). "Thus, it is likely that Id2 promotes tumor initiation through inhibition of the Mxd1–Max network and activation of the c-Myc–Max." (PMID 26163528, 2015). "In order to determine if the therapeutic effect of the Id2-kd N2a whole tumor cell vaccine could be enhanced, we elected to combine this therapy with immune checkpoint blockade in the form of anti-cytotoxic T lymphocyte associated antigen 4 (CTLA-4) antibody." (PMID 26079374, 2015). "The mechanism of tumor cell immunogenicity in Id2-kd cells is unknown, but is clearly a perturbation in molecular homeostasis of the tumor cells." (PMID 26079374, 2015). "In contrast, when wild type cells were injected into both hind legs 5 days apart, tumors grew aggressively on both sides, suggesting the absence of concomitant immunity in the wild type Neuro2a, validating the immunogenicity and potential use of Id2-kd N2a cells as a tumor vaccine." (PMID 26079374, 2015). "Implantation of Id2-kd N2a cells surprisingly resulted in tumor rejection in 60% of mice and these mice were subsequently protected against further wild-type Neuro2a tumor cell challenge." (PMID 26079374, 2015). "To investigate the genes that could be involved in the inhibition of ileal tumor formation in Apc Id2 mice, we next performed DNA microarray analysis of ileal crypts that were isolated from ApcΔ716 and Apc Id2 mice." (PMID 26163528, 2015). "Although the general role of Id2 proteins has been considered pro-growth and anti-differentiation in various human tumors, their role in modulating invasion and metastasis of some specific tumor cells remain to be investigated." (PMID 19257909, 2009). "Altogether, these results suggest that ID2 may play an important role in tumor initiation and progression." (PMID 19129913, 2009). "In malignant tissues, ID2 expression has been detected in both the nuclear and cytoplasmic compartments, but we have demonstrated that only nuclear expression of ID2 is inversely correlated with the differentiation grade of the tumor (p = 0.007)." (PMID 19129913, 2009). "The tumor suppressor role of Id4 appears to be unique as compared to other members of the Id gene family (Id1, Id2 and Id3) that may act as oncogenes or co-operating oncogenes in many cancers." (PMID 19500415, 2009). "In addition, high level of overall Id-2 expression in primary tumour predicted better survival of ESCC patient in Kaplan–Meier analysis (P=0.041)." (PMID 18000500, 2007).
tumor (continued). "Similarly, ID2 was strongly enriched in tumors with short tumor latency." (PMID 40161734, 2025). "Our study demonstrates that Id2-mediated transcriptional and epigenetic modifications play a crucial role in hierarchical T-cell exhaustion, and the mechanistic insights gained may have implications for therapeutic intervention with tumor immune evasion." (PMID 38287103, 2024). "Our study demonstrates that Id2 drives T-cell exhaustion in a transcriptional and epigenetic manner and might be harnessed for therapeutic interventions to reverse T-cell exhaustion and restrain tumor progression." (PMID 38287103, 2024). "However, they do not address the possible contribution of ID2 to the regulation of biological functions associated to tumour-associated myeloid cells in the context of GB." (PMID 39019900, 2024). "In addition, mice that lack Id2 develop intestinal adenomas, and show a hyperproliferation of colon stem cells during embryonic development due to increased Wnt/B-catenin signaling, suggesting that ID2 may function as a tumor suppressor in other cell types." (PMID 35990659, 2022). "ID2 (DNA binding protein inhibitor 2) is a helix-loop-helix TF that positively regulates cancer cells’ proliferation, migration, invasion, and cell cycle progression, and also negatively regulates cancer cells’ differentiation and apoptosis, as well as other tumor suppressor genes." (PMID 36101460, 2022). "Although these data indicate that Id2 and Aldh3a1 expression is required for efficient tumour growth in the brain, they do not address whether these genes play a role in promoting brain colonisation of tumour cells from the circulation." (PMID 30642388, 2019). "Moreover, elevated Id2 and Aldh3a1 protein levels were detected by immunoblotting in the original brain-derived sublines as well as in the independent sublines isolated from the brains of tumour-bearing mice." (PMID 30642388, 2019). "Indeed, pimozide suppresses Id2 expression and reduces tumor growth." (PMID 28122577, 2017). "Importantly, there was a consistent and significant reduction in the extent of tumor-cell metastasis/dissemination of the Id2-knockdown cells in the mice compared with that of the control cells, indicating that the Id2 knockdown significantly impaired the metastatic potential of the CSCs." (PMID 26965643, 2016). "Therefore, careful evaluation is required to unambiguously identify the tumor cell types or subtypes that may use Id2 to control their different phenotypes." (PMID 19257909, 2009). "However, results obtained in other models suggest that the action of ID2 could depend on the inhibition of Rb tumor suppressor pathway." (PMID 19129913, 2009). "Finally, although our results are preliminary, they suggest that ID2 could be involved in the tumor dedifferentiation processes of NSCLC, and could be used as prognosis marker for patients with poorly differentiated tumors." (PMID 19129913, 2009). "Under hypoxia, ID2 directly binds and disrupts the VHL-Elongin C complex, stabilizing the HIF in tumor cells and promoting survival during metabolic stress (left side)." (PMID 41155273, 2025). "Butyrate, for instance, upregulates the expression of inhibiting DNA binding 2 (ID2) in CD8+ T cells, thereby augmenting the anti-tumor cytotoxicity of CD8+ T cells." (PMID 38617841, 2024). "Id2 ablation also led to decreased frequencies of adoptive Ki-67-expressing OVA-specific CD8+ T cells in tumors and tumor-draining lymph nodes (tdLNs)." (PMID 38287103, 2024). "Collectively, our study demonstrates that Id2-mediated transcriptional and epigenetic modifications play a crucial role in hierarchical T-cell exhaustion, and the mechanistic insights gained may have implications for therapeutic intervention with tumor immune evasion." (PMID 38287103, 2024).